TFRC (transferrin receptor)
Diseases named in the same sentence as TFRC in open-access papers (continued):
Sharing a sentence is not in itself a finding about the gene and the disease.
cancer (continued). "The absence of CD71, the transferrin receptor, has been reported in dormant lymphocytes and in cancer stem cells." (PMID 23767415, 2013). "CD71 (the transferrin receptor) is absent in un-stimulated peripheral blood lymphocytes, in some cancer stem cells and in long term culture-initiating cells from normal bone marrow." (PMID 23767415, 2013). "Thus, TFRC presents a compelling molecular target for cancer therapy, yet its role in ESCA has not been fully established." (PMID 40302812, 2025). "Because certain CSCs express transferrin receptor (TFRC) and prostate-specific membrane antigen (PSMA), TFRC and PSMA could be useful biomarkers for the directed imaging and targeted therapy of CSCs in cancer care." (PMID 38067237, 2023). "Levels of TFRC (P<0.001), PHKG2 (P=0.005), FADS2 (P<0.001), and NOX1 (P=0.011) mRNA relative expression were higher in cancer cells than in immune cells, whereas levels of ALOX5 (P<0.001) mRNA relative expression were lower in cancer cells than in immune cells." (PMID 35866375, 2022). "CALAA-01 is another transferrin receptor-targeted NP encapsulating siRNA which acts against the M2 subunit of ribonucleotide reductase (RRM2), and it has shown potential antineoplastic activity in phase I trials which involve patients with a variety of cancers." (PMID 31097014, 2019). "For example, a protein with relatively high expression such as the transferrin receptor, even though differentially expressed in cancer and normal cells, would not be suitable for delivering a toxin because the normal cells would internalize sufficient toxin to kill the cell." (PMID 24511425, 2013). "Consequently, a wide spectrum of cellular receptors and proteins, including transferrin receptor, insulin-like growth factor 1 (IGF-1) receptor, folate receptor or integrins has been widely investigated to date as factors for increasing drug selectivity against cancer cells." (PMID 34771587, 2021). "In summary, except for CDKN2A, which is a clear outlier in the dataset under consideration, the changes in the local number of CNVs did not appear to be connected to the pan-cancer genes located in these regions (CAMTA1 and MTOR, MUC4 and TFRC, and NCOR2)." (PMID 31783642, 2019). "Other difficulties appear due to the non-expression of most common cancer cell surface markers (e.g., HER2 receptor, Transferrin receptor) by CSCs and common expression of most cell surface markers by both the CSCs and healthy stem cells." (PMID 28785557, 2017). "For the Test Cancer BioChip, the negative controls employed included non-targeting, ACTB, GUSB, GAPDH, RPLP0, TFRC and cyclophilin siRNA as well as no siRNA." (PMID 23049944, 2012). "The increased TFRC, PHKG2, FADS2, NOX1, and reduced ALOX5 levels in LUSC tissues were reported in the present study, and scRNA-seq analysis showed that the levels of the five dysregulated genes were mainly influenced by cancer cells rather than immune cells." (PMID 35866375, 2022). "While the small number of cancer samples did not allow assessment of statistical significance, several of the new markers identified through mRNA analysis also showed trends of increased protein expression in SQCCs relative to ADCs (CD71/TFRC, CD9, PDPN, CD138/SDC1, CD99)." (PMID 25551685, 2014).
infection (207 papers, 2006 to 2026). The state of being infected such as from the introduction of a foreign agent such as serum, vaccine, antigenic substance or organism. "Expression of angiotensin-converting enzyme 2 (ACE2) and transferrin receptor 1 (TfR1), a ferroptosis marker and alternative viral entry receptor, was significantly upregulated post-infection in a variant-dependent manner." (PMID 40861496, 2025). "Metrics typically used to assess iron status, such as serum ferritin and soluble transferrin receptor (sTfR), are altered by inflammatory mechanisms associated with the body’s acute-phase response to infection." (PMID 40632804, 2025). "Importantly, we demonstrated that PPRV infection causes aberrant cellular iron accumulation by increasing transferrin receptor (TFRC) expression and that iron accumulation induces reticulophagy and ferroptosis, which benefits PPRV replication." (PMID 40126010, 2025). "The mechanisms that could lead to a higher reticulocytes infection in CM patients might be linked to specific protein-protein interactions similar to what is observed for P. vivax, which binds TFRC via the RBP2b protein to target reticulocyte cells specifically." (PMID 38297098, 2024). "Of the 9 TN-specific proteins, 6 proteins (CRP, LBP, LRG1, SAA1, TFRC) overlapped with the WT group identifying them as infection-specific and toxin-independent proteins (black text)." (PMID 41326716, 2026). "In this study, we analyzed the effect of giant panda transferrin receptor 1 (gpTfR1) on pFPV-sc infection." (PMID 40711262, 2025). "Western blotting demonstrated that the levels of NCOA4 and TFRC were upregulated after 24 h infection compared to controls, indicating that ASFV infection facilitated NCOA4-mediated ferritinophagy." (PMID 40548711, 2025). "No significant changes in the expression levels of the ferritin subunits (FtH and FtL) and transferrin receptor 1 (Tfr1) were observed in response to the infection across different genotypes at both the protein and mRNA level, respectively." (PMID 38301068, 2024). "Inhibiting TFRC dramatically augments infection by mitigating lipid peroxidation, indicating potential resistance to infection with increased ferroptosis." (PMID 39666228, 2024). "Based on the existing studies on the expression level of cell surface transferrin receptor-1 and infection by PEDV virus." (PMID 36936772, 2023). "Upon infection, macrophages induce the formation and release of extracellular vesicles (EV), containing iron protein, such as transferrin receptor (TfR), LDL-related 64 protein 1 (CD91), and hemoglobin-haptoglobin receptor (CD163)." (PMID 37512874, 2023). "Transferrin receptor 1 (TfR1), which mediates cellular iron uptake, was upregulated after the TgCtwh3 infection." (PMID 37651502, 2023). "Western blots for viral antigen at 4 h post-infection revealed approximately 50 to 60% lower levels of nucleoprotein (NP) in A549 TFRC KO cells compared to A549 CTRL, consistent with an involvement of TfR1 in IAV entry or early replication steps." (PMID 37192162, 2023). "Treatment of MoDCs with iron citrate (FeC6H5O7), prior to and during infection, induced cellular iron loading, as indicated by reduced TFRC expression." (PMID 35121793, 2022). "At the same time, there is an increased expression of the receptor TfR1/CD71 (transferrin receptor protein—cluster of differentiation), important for the entrance of the virus, thereby potentiating the infection." (PMID 36016325, 2022). "One bulging area of the capsid known as the threefold spike, containing epitopes involved in transferrin receptor (TfR) binding and infection, is critical in controlling both the antigenicity and host range of FPV and CPV." (PMID 35198456, 2021). "In the first phase of infection, hepcidin is more highly expressed in order to sustain the virus internalization though the iron importer, transferrin receptor 1 (TfR1)." (PMID 33921027, 2021).
infection (continued). "Since T cells following activation/infection can upregulate CD71 (the transferrin receptor), we measured the surface expression of CD71 on splenic T cells." (PMID 33329589, 2020). "The global network notably recognizes six proteins (EPHA2, FBL, PFKM, PSMA5, SSR1, and TFRC) for their involvement in the infection of cells (p: 9.58 × 10− 4)." (PMID 31159726, 2019). "To minimize the impact of infections and inflammation, we used transferrin receptor, as recommended by WHO." (PMID 30669431, 2019). "Ferritin and transferrin receptor expression were upregulated by infection (main effects, p < 0.001 and p = 0.005, respectively)." (PMID 30778359, 2018). "Conversely, the spleen and lung displayed far fewer effects and were altered only by infection, except for spleen transferrin receptor expression, which was altered by diet × infection (p = 0.001)." (PMID 30778359, 2018). "PBMC TFRC expression was upregulated by ID diet (main effect, p = 0.002), and reduced by infection (main effect, p = 0.008)." (PMID 30778359, 2018). "Herein, we have identified a role for Encephalitozoon hellem polar tube protein 4 (PTP4) in infection demonstrating that PTP4 can bind to the host cell surface via the host transferrin receptor 1 (TfR1) protein." (PMID 28426751, 2017). "We observed that transmembrane basolateral plasma membrane proteins not known to be involved in EPEC infection, AQP3-EGFP and the Transferrin receptor tagged with mCherry, were recruited to the infection site, where they accumulated at the EPEC microcolony." (PMID 28636623, 2017). "Structural studies have shown that this region interacts with the transferrin receptor (TFR) of the host cell to mediate infection, defines the host range, and is highly antigenic." (PMID 28707272, 2017). "For example, a multimerized aptamer targeted against Transferrin receptor (TfR), which was intially selected against human transferrin receptor, was also shown to block infection of recombinant New World Hemorrhagic Fever Mammarenaviruses (NWM) in human cells." (PMID 28850067, 2017). "A clear difference in expression of iron regulatory genes was observed with a consistent and significant down-regulation of FTH1, SLC11A1, SLC11A2, HMOX1 and TFRC in animals controlling the infection." (PMID 24505407, 2014). "The loss of tetherin expression was somewhat specific, as β-actin and transferrin receptor protein levels were unaffected up to 16 h after infection and GAPDH levels were only slightly reduced." (PMID 24067975, 2013). "Clade B NW arenaviruses employ the transferrin receptor 1 (TfR1) as an entry receptor for the infection of target cells, while the cellular receptor for Clade A NW arenaviruses has not yet been identified." (PMID 23202512, 2012). "To determine if the transferrin recycling pathway is involved in Hp colonization of the cell surface, we silenced transferrin receptor expression during infection." (PMID 21589900, 2011). "This was confirmed by comparing the expression level of the transferrin receptor in Francisella-infected macrophages to the level found in uninfected cells by immunblotting at one hour and twenty-four hours after infection." (PMID 20184753, 2010). "The transferrin receptor TfR1 plays an important part for delivering iron to the host cell during infection." (PMID 20184753, 2010). "Infection was transferrin receptor 1 (TfR1)-dependent and the surface expression of TfR1 was higher in infected cultures, suggesting a novel arenaviral dissemination strategy in hematopoietic progenitor cells." (PMID 20419155, 2010). "This is followed by a response at the transcriptional level of transferrin receptor mRNA at 24 h of infection." (PMID 20184753, 2010). "Infection with Ehrlichia chafeensis and E. sennetsu changes the binding affinities for IRP-1 during the first hours of infection with a concomitant increase in levels of transferrin receptor." (PMID 20184753, 2010).
infection (continued). "Since little is known about TfR1 in macrophages infected with Francisella, we investigated the role of the transferrin receptor during infection and its relation to the maturation of the Francisella-containing vacuole (FCV)." (PMID 20184753, 2010). "Increased iron-responsive element–IRP interaction and transferrin receptor 1 expressions in spleen-derived macrophages from LD-infected mice confirm that LD employs similar mechanism to acquire iron during infection into mammalian hosts." (PMID 18823384, 2009). "In areas with a limited infection pressure, soluble transferrin receptor (sTfR) has been shown to be a promising new tool for the diagnosis of deficiency of iron stores." (PMID 19946096, 2009). "The regulation of the transferrin receptor/ESAG6/7 proteins in T. congolense upon TcREG9.1 silencing matched the upregulation for these transcripts when T. congolense progresses from ascending to peak parasitaemia’s infection in vivo." (PMID 38408115, 2024). "Transferrin receptor protein 1 (TFRC), the main receptor for cellular iron uptake into cells, is ubiquitously expressed in all tissues and plays a significant role in carrying iron to the host cell during infection and inflammation." (PMID 39189262, 2024). "Several New World arenaviruses employ transferrin receptor 1 (TfR1) to initiate infection." (PMID 35235462, 2022). "On day 15 of infection, Ag-expCD4+ T cells expressed lower levels of Glut-1 (a glucose transporter), CD98 (a component of the Slc7a5 heterodimeric large neutral amino acid transporter), and CD71 (a transferrin receptor) than Ag-expCD4+ T cells from day 5 of infection." (PMID 32817333, 2020). "Furthermore, some viruses, including zoonitic ones, have been identified to utilize human transferrin receptor for viral entry and infection." (PMID 32325910, 2020). "Liver TFRC expression was altered by a diet × infection interaction (p = 0.013)." (PMID 30778359, 2018). "Because of these links to host cell recycling, we next tested whether infection with Y. pestis impacts host cell recycling by monitoring recycling of the host transferrin receptor (TfR)." (PMID 29463656, 2018). "Mouse transferrin receptor 1 (mTfR1) is used by MMTV to initiate infection of murine cells." (PMID 25980759, 2015). "To directly test if the transferrin receptor pathway is important for Hp colonization of the polarized epithelium, we silenced expression of the transferrin receptor during infection and asked whether this affects microcolony growth." (PMID 21589900, 2011). "We then further investigated whether TFRC affected STAT3 expression in cardiomyocytes, and found that overexpression of TFRC in cardiomyocytes by AAV9‐flag‐TFRC infection significantly increased STAT3 and phosphroylated STAT3 (p‐STAT3) expression, and Ccl2 mRNA expression." (PMID 37647427, 2023). "Furthermore, in a mixed infection of male volunteers, expression of both lactoferrin and transferrin receptors gave a competitive advantage over a strain expressing only the transferrin receptor, thereby further indicating a role in virulence for iron acquisition from lactoferrin." (PMID 24312900, 2013). "Importantly, a transferrin receptor mutant (ΔtbpA ΔtbpB) for N. gonorrhoeae was unable to initiate urethritis in human volunteers, demonstrating that a bacterial iron acquisition system is an essential virulence factor for human infection." (PMID 24312900, 2013). "As a readout of the iron status of Gc, we analyzed the TonB-dependent transferrin receptor TbpAB (NGO1495-NGO1496), which is required for symptomatic infection in male urethral challenge and shows Fur-dependent repression of expression in high iron conditions." (PMID 38976720, 2024). "Thus, it could be inferred that TFRC may play an important role in CVB3-induced infection." (PMID 35821227, 2022).
infection (continued). "Fibroblast growth factor (FGF)-23, TFRC, FGFR4, and ATPase H+ transporting V0 subunit B (ATP6V0B) were the upregulated genes identified in A. baumannii without resistant gene infection-associated pulmonary host responses." (PMID 39857726, 2025). "Authors concluded that the transferrin receptor 1 is not essential for infection and that a different cell surface molecule mediates the MMTV entry into human cells." (PMID 36016325, 2022). "Nevertheless, expression of a functional lactoferrin receptor in N. gonorrhoeae provided a competitive advantage in a human infection model, and it was essential for infection by a strain lacking the transferrin receptor." (PMID 28670572, 2017). "Similarly, the transferrin receptor (TfR), which is predominantly localized to basolateral membranes and recycling endosomes, was also recruited to the EPEC infection site." (PMID 28636623, 2017). "Infection increased expression of the macrophage mannose receptor 1-like (MR) gene between 5 h and 8 h, the tapasin-like (TAPBP) gene at 5 h and 6 h, and the transferrin receptor 1a (TfR) gene at 4 h." (PMID 25496447, 2014). "In contrast, concentrations of soluble transferrin receptor (sTfR), a sensitive indicator of ID at the tissue level, remain unaltered in inflammation and in most, although not all, infections." (PMID 22574149, 2012). "Guided by the known use of human transferrin receptor 1 (hTfR1) by several NWAs for cell entry, we conducted a structure-based virtual screening campaign targeting the MACV GP1-hTfR1 interaction interface to identify small molecules capable of inhibiting early infection." (PMID 42077170, 2026). "Moreover, considering the absence of a nucleus and mRNA within mature erythrocytes, and the subsequent absence of further protein synthesis, the presence of the TFRC must have preceded the parasite’s infection of the red blood cell." (PMID 38297098, 2024). "The observation that the transferrin receptor in N. gonorrhoeae was required for experimental infection of the human male urethra in strains naturally lacking lactoferrin receptors provided additional support for targeting the transferrin receptor in a vaccine." (PMID 36683691, 2022). "For instance, infection with the New World mammarenavirus Junin virus has been shown to induce the PI3K/Akt pathway, and inhibition of this pathway has resulted in a decreased infectious virus yield because of blocking the recycling of the transferrin receptor engaged in JUNV cell entry." (PMID 31708904, 2019). "Consistent with reports in the literature, HAdV-C2 infection was associated with a significant reduction in total tumor necrosis factor receptor (TNFR1) protein, but did not significantly alter total protein levels of the transferrin receptor (TfR)." (PMID 31425554, 2019). "However, in vivo experiments demonstrated that the expression of the lactoferrin receptor in the absence of the transferrin receptor is sufficient for establishment of infection." (PMID 24312900, 2013). "Restoration of a functional lactoferrin receptor in the strain lacking the transferrin receptor enabled it to establish infection in a substantial proportion of the volunteers, demonstrating that either receptor could support growth on the mucosal surface of the male genitourinary tract." (PMID 30837995, 2019). "Importantly, the knockout of TFRC did not diminish the effects of mGluR2 and KCa1.1 on FCV infection." (PMID 41150120, 2025).
metabolic disease (15 papers, 2016 to 2026). A congenital disorder (due to inherited enzyme abnormality) or acquired (due to failure of a metabolically important organ) disorder resulting from an abnormal metabolic process. "circRNA-TFRC (transferrin receptor) has also been associated with IR, and the overexpression of TFRC can aggravate the risk of T2DM and metabolic diseases." (PMID 32560220, 2020).
neurological diseases (10 papers, 2017 to 2026). "It is believed that this is a promising route for delivering drugs into the brain of patients with neurological disorders; however, despite decades of research to develop transferrin receptor (TfR) binding antibody-drug conjugates, there has been little clinical success." (PMID 32842549, 2020). "In addition, the blood exosomes exhibit “transferrin receptor” (TfR) to enhance the drug accumulation, which may be attributed to the natural ability of blood exosomes in targeting neurological diseases without any modifications." (PMID 32957534, 2020).
bacterial infection (7 papers, 2015 to 2024). "During bacterial infection, to restrict the bacteria from iron acquisition, macrophages take up iron via receptors including hemoglobin‐haptoglobin receptor (CD163), transferrin receptor (TfR) and lipoprotein receptor‐related protein 1 (LRP1)." (PMID 38247172, 2024).